SIRT1 (sirtuin 1)
Diseases named in the same sentence as SIRT1 in open-access papers (continued):
Sharing a sentence is not in itself a finding about the gene and the disease.
pancreatic cancer (continued). "In light of the literature presented here, further basic research is warranted in order to establish possible therapeutic strategies for ovarian, thyroid and pancreatic cancer, where a pro-tumorigenic role for SIRT1 has been established." (PMID 30319549, 2018). "SIRT1 has been shown to inhibit pancreatic cancer cell proliferation and express oncogenic pancreatic adenocarcinoma-upregulated factors by inhibition of β-catenin and cyclin-D129." (PMID 28600541, 2017). "SIRT1 inhibits the proliferation of pancreatic cancer cells by expressing oncogenic pancreatic adenocarcinoma upregulated factor (PAUF) and inhibition of β-catenin and cyclin-D129." (PMID 28600541, 2017). "On the contrary, SIRT1 facilitated chemoresistance in pancreatic cancer cells and the inhibition of SIRT1 sensitizes to gemcitabine." (PMID 29100388, 2017). "Mechanistically, E-cadherin transcriptional repression has been directly related to SIRT1 in pancreatic cancer." (PMID 27379175, 2016). "We extended our findings on tumor development to tumor progression, where we also found that SIRT1 stimulated the proliferation of established pancreatic tumor cells, in line with previous reports." (PMID 27494892, 2016). "SIRT1 has been shown to regulate acinar-to-ductal metaplasia and promote tumorigenesis and metastases in pancreatic cancer." (PMID 27379175, 2016). "Our data do not only reinforce the idea to explore SIRT1 as a druggable target in early stage pancreatic cancer, we also deciphered a relation with tumor metabolism." (PMID 27494892, 2016). "Complementary to our in vivo observations in the mice, we down-regulated SIRT1 gene expression using siRNA in a human pancreatic tumor cell line." (PMID 27494892, 2016). "Adding to these findings, Deng S. and colleagues demonstrated that miR-217 is downregulated in pancreatic cancer and was negatively correlated with sirtuin 1 (SIRT1), its direct target." (PMID 27187371, 2016). "In conclusion, our new results underscore a novel oncogenic function of SIRT1 during pancreatic cancer development where it stimulates the proliferation and expression of glycolytic proteins." (PMID 27494892, 2016). "It is also reported to exert anti-apoptotic effects on pancreatic cancer cells through activation of AMPK/Sirtuin-1 signaling pathway." (PMID 27119501, 2016). "In particular, the TGF-β1 driven EMT of pancreatic cancer cells upregulates SIRT1 expression, while knockdown of the histone deacetylase is able to revert the cell phenotype via mesenchymal-epithelial transition (MET)." (PMID 27379175, 2016). "We therefore have undertaken a novel study investigating the role of SIRT1-7 protein expression in a cohort of pancreatic tumours." (PMID 26121130, 2015). "We undertook a novel study investigating SIRT1-7 protein expression in a cohort of pancreatic tumours." (PMID 26121130, 2015). "The few studies that have been performed investigating SIRTs role in pancreatic cancer have produced contrasting results for SIRT1, with both SIRT1 inhibitors and activators being suggested as novel therapeutic targets." (PMID 26121130, 2015). "There have been few studies investigating sirtuins in pancreatic cancer, the majority of which have focused on SIRT1." (PMID 26121130, 2015). "In no doubt, this study warrants further investigation of the role of Sirt1 in pancreatic cancer development as well as of the chemotherapeutic efficacy of Sirt1 inhibitors in preclinical models of human PDAC, guided by the expression of Sirt1 and Ccar2." (PMID 25594010, 2014). "Several studies have shown that inhibition of Sirt1 and Sirt2 in human pancreatic cancer cell lines can significantly inhibit cell proliferation and induce apoptosis." (PMID 25051362, 2014). "Clinical epidemiological studies have also found that Sirt1 is overexpressed in pancreatic cancer tissues at both the mRNA and protein levels compared with adjacent normal pancreatic tissues." (PMID 25051362, 2014).
pancreatic cancer (continued). "A recent study by Nalls and colleagues showed that SAHA-induced micro-RNA 34a (miR34a) expression in human pancreatic cancer cells putatively directly inhibited Sirt1 expression by binding within the 3’UTR of Sirt1." (PMID 24088390, 2013). "Sirt1 is an independent prognosticator in PDACs and plays an important role in pancreatic cancer cell growth, which can be levered out by small molecule inhibition." (PMID 24088390, 2013). "Accordingly, overexpression of Sirt1 led to increased cell viability, while small molecule inhibition led to a growth arrest in pancreatic cancer cells and impaired cell survival." (PMID 24088390, 2013). "SIRT1 is up regulated in pancreatic cancer, which is a NAD dependent deactylase and has been shown to inhibit several pro-apoptotic genes." (PMID 21909380, 2011). "Since Sirts regulate tumor formation and angiogenesis, we next examined the effects of resveratrol on the expression of Sirt1, Sirt2 and Sirt3 in pancreatic cancer cells by q-RT-PCR." (PMID 21980390, 2011). "Moreover, research has shown that hypoxia-induced exosomal circZNF91 can bind competitively to miR-23b-3p in normoxic pancreatic cancer cells, relieving the suppression of SIRT1 by miR-23b-3p." (PMID 39928285, 2025). "Additionally, SIRT1 also modulates the chemoresistance of pancreatic cancer through its interaction with hypoxic exosomal circular RNA (circRNA), particularly circZNF91." (PMID 39682281, 2024). "In pancreatic cancer, SIRT1 regulates adenohypophysis to ductal chemotaxis (ADM) through deacetylation of pancreatic transcription factor-1a and β-catenin, which enhances cell viability in pancreatic cancer, thereby promoting cell proliferation and tumor formation." (PMID 39479446, 2024). "The elevated SIRT1 then stabilizes the hypoxia-inducible factor 1 α (HIF1α) protein through deacetylation, which subsequently promotes glycolytic metabolism and contributes to the chemoresistance observed in pancreatic cancer cells." (PMID 39682281, 2024). "In pancreatic cancer, SIRT1 was reported to promote proliferation, autophagy and invasion." (PMID 37293593, 2023). "In this positive feedback loop, circZNF91 upregulated SIRT1 expression via competitively binding to miR-23b-3p and SIRT1 stabilizes HIF-1α protein via decreasing the acetylation of HIF-1α in pancreatic carcinoma (PC) cells,thus increasing the protein level of HIF-1α." (PMID 37213665, 2023). "Our previous study demonstrated that the CRL4B complex could coordinate with SIRT1 to regulate pancreatic cancer metastasis and stem cell properties to promote tumorigenesis." (PMID 35534547, 2022). "SIRT1 overexpression regulates doxorubicin resistance in breast tumor by activating the Akt pathway, and SIRT1 promotes tumor growth in colorectal, breast, and pancreatic cancers." (PMID 35212616, 2022). "Loss of Sirtuin 1 (SIRT1) induces NF-κB signaling in cachectic muscles, activating the expression of FOXO and NADPH oxidase 4 (Nox4), which trigger protein degradation pathways in pancreatic cancer." (PMID 36077789, 2022). "Previous studies have shown an important pro-tumoral role for SIRT1 in pancreatic cancer." (PMID 34163012, 2021). "In addition, SIRT1 has been shown to facilitate pancreatic cancer chemoresistance, while application of a combination therapy consisting of a SIRT1 inhibitor and gemcitabine has been shown to have enhanced efficacy for pancreatic cancer." (PMID 34907162, 2021). "To further elucidate whether SIRT1 and CUL4B promote the development of pancreatic cancer cells into CSCs, repopulating from single cells, we analyzed the effect of SIRT1 and CUL4B on sphere formation." (PMID 34163012, 2021). "Additionally, previous study revealed that overexpression of SIRT1 reversed the function of miR-601 on pancreatic cancer cells." (PMID 33955831, 2021). "Here, we found that SIRT1 was highly expressed in pancreatic cancer cells." (PMID 34907162, 2021).
pancreatic cancer (continued). "In this study, we analyzed the potential role of SIRT1 in pancreatic cancer development." (PMID 34163012, 2021). "Moreover, SIRT1 facilitates chemoresistance of pancreatic cancer cells by regulating adaptive responses to chemotherapy-induced stress, and combination therapy with SIRT1 inhibitor and gemcitabine was shown to have enhanced efficacy for pancreatic carcinoma." (PMID 34163012, 2021). "In addition, SIRT1 has been shown to promote the proliferation and metastasis of human pancreatic cancer cells." (PMID 34907162, 2021). "E-cadherin transcription inhibition is directly related to SIRT1 in pancreatic cancer." (PMID 34163012, 2021). "Furthermore, in lung and pancreatic cancer, activation of SIRT1 has been shown to enhance cancer cell sensitivity to classic chemotherapy." (PMID 32051395, 2020). "Similarly, alisertib (ALS), a potent and selective Aurora kinase A inhibitor, induces cell cycle arrest and autophagy and suppresses EMT involving PI3K/Akt/mTOR and SIRT1-mediated signaling pathways in human pancreatic cancer cells." (PMID 33042011, 2020). "The sensitivity of pancreatic cancer cells to the Sirt1/2 inhibitor Tenovin-6 correlates with the levels of SIRT1/Dbc1 suggesting that Dbc1 can be a biomarker for those pancreatic tumors that could benefit from SIRT1-inhibitory drugs." (PMID 33042011, 2020). "Additionally, blocking SIRT1 activity with specific inhibitors was suggested to reverse the chemoresistance of both gastric and pancreatic cancers." (PMID 28977971, 2017). "Furthermore, EMT in pancreatic cancer cells, induced by transforming growth factor‐β (TGF‐β), is associated with upregulation of SIRT1, while inhibition of SIRT1 induced mesenchymal–epithelial transition." (PMID 28994177, 2017). "However, our study showed that SIRT1 was decreased in the pancreatic cancer cell cytoplasm and mostly localized to the nucleus." (PMID 28052003, 2017). "Our research indicates that SIRT1 and FoxO1 may synergistically mediate autophagy under metabolic stress by forming a functional complex in pancreatic cancer cells." (PMID 28052003, 2017). "It was interesting to find that SIRT1 may repress pancreatic cancer cell development via multiple mechanisms, which makes miR-138-5p a potential target for tumor therapy." (PMID 28052003, 2017). "c-Myc and SIRT1 expression levels were inversely correlated with miR-494 expression in pancreatic cancer tissues due to direct interaction with the 3′UTR with the mRNA transcripts of both c-Myc and SIRT1, and restoring miR-494 sensitized the cells to chemotherapy." (PMID 27242892, 2016). "Notably, treatment with the SIRT1 inhibitor EX527 reduced the proliferation of pancreatic cancer cells and enhanced their sensitivity to gemcitabine in vitro, but no apparent effects on EMT were seen." (PMID 27379175, 2016). "A previous study reported that SIRT1 mRNA and protein are overexpressed in pancreatic cancer tissues, and increased SIRT1 expression was correlated with tumours from patients > 60 years of age, or with tumours > 4 cm, a higher TNM stage or the presence of lymph node or hepatic metastases." (PMID 27793039, 2016). "Interestingly, miR-217 negatively regulates SIRT1 mRNA translation, thus suggesting dysregulation of the miR-217-SIRT1 axis in response to the inflammatory environment of pancreatic carcinoma." (PMID 27379175, 2016). "Furthermore, adiponectin has been shown to utilize SIRT1 expression in many biological responses, including protection of liver from alcoholic/non-alcoholic damage and inhibition of apoptosis in pancreatic cancer cell." (PMID 25961287, 2015). "Given the anti-apoptotic effect of adiponectin on the pancreas and heart, we hypothesized that adiponectin may increase mitochondrial biogenesis and inhibit apoptosis of pancreatic cancer cells via AMPK/Sirt1/PGC1α." (PMID 25051362, 2014). "Reports that explore Sirt1 function in pancreatic cancer are sparse." (PMID 24088390, 2013).
pancreatic cancer (continued). "Furthermore, we investigated the impact of overexpression and small molecule inhibition on Sirt1 in pancreatic cancer cell culture models including combinatorial treatment with chemotherapy and EGFR-inhibition." (PMID 24088390, 2013). "Consequently, targeting SIRT1 represents a promising therapeutic strategy for overcoming drug resistance and improving treatment outcomes in this aggressive malignancy, underscoring its potential as a strategic target for intervention in pancreatic cancer." (PMID 39682281, 2024). "Furthermore, our results suggest that the induction of SIRT1 by 1,25(OH)2D3 might be a general mechanism which also occurs in melanoma and pancreatic cancer." (PMID 39494323, 2024). "Therefore, the aim of our study was to evaluate the impact of metformin on histone acetyltransferases (HATs) (i.e., p300/CBP-associated factor (PCAF), p300, and CBP) and on histone deacetylases (HDACs) (i.e., SIRT-1 in human pancreatic cancer (PC) cell lines, 1.2B4, and PANC-1)." (PMID 36678613, 2023). "They first demonstrated the ability of miR-217 to negatively regulate the 3′UTR of SIRT1, causing a decrease in SIRT1 mRNA translation; in the same study, SIRT1 knockdown was strictly connected with mesenchymal-to-epithelial transition (MET) in pancreatic cancer cells." (PMID 35745656, 2022). "However, SIRT1 inhibition in vivo was found to promote pancreatic cancer xenograft tumor growth." (PMID 34907162, 2021). "Thus, SIRT1 is an important regulatory protein in pancreatic cancer." (PMID 34907162, 2021). "Furthermore, SIRT1 significantly promoted the growth of pancreatic tumors." (PMID 34163012, 2021). "Conversely, another study has suggested that activation of SIRT1 inhibited the proliferation of pancreatic cancer cells that expressed the oncogene pancreatic adenocarcinoma up-regulated factor (PAUF) and that SIRT1 activation could be a novel therapeutic strategy." (PMID 26121130, 2015). "For instance, SIRT1 and SIRT7 were reported to promote pancreatic cancer progression, while SIRT2, SIRT4, SIRT5, and SIRT6 seem to play a tumor suppressor role." (PMID 41391757, 2025). "This suggests that the current method to inhibiting SIRT1 by EX527 in vitro and in vivo both pancreatic tumor models is unexpectedly the opposite of what was seen in vitro." (PMID 39403142, 2024). "By suppressing the promoters of the target genes, forkhead transcription factor 3 (FOXO3) and GRHL3, the SIRT1/CRL4B complex encourages the migratory and invasive capacity of pancreatic cancer cells." (PMID 39479446, 2024). "This study found that AMPK phosphorylation upregulates SIRT1, which in turn reciprocally phosphorylates AMPK, establishing a regulatory feedback loop that is crucial for pancreatic cancer cell survival." (PMID 39682281, 2024). "circPTPN22 is upregulated in pancreatic cancer, and it interacts directly with STAT3 to block the interaction between STAT3 and SIRT1." (PMID 36467402, 2022). "We next investigated the role of the SIRT1/CRL4B complex in proliferation, autophagy, and metastasis of pancreatic cancer cells." (PMID 34163012, 2021). "Strikingly, SIRT1 and CUL4B expression is markedly upregulated in a variety of human cancers, including pancreatic cancer." (PMID 34163012, 2021). "We demonstrated that SIRT1 and CUL4B positively regulate CSC-like features in pancreatic cancer cells." (PMID 34163012, 2021). "To further confirm the in vitro interaction between SIRT1 and the CRL4B complex, we performed co-IP assays in four pancreatic carcinoma cell lines, and the results demonstrated that SIRT1 co-immunoprecipitated with the CRL4B complex, rather than CRL4A complex." (PMID 34163012, 2021). "The SIRT1 inhibitor 6-chloro-2,3,4,9-tetrahydro-1 H-Carbazole-1-carboxamide (EX527) enhanced sensitivity of pancreatic cancer cells to GEM treatment through increased apoptosis." (PMID 33042011, 2020).
pancreatic cancer (continued). "The results suggest that pancreatic cancer cells are similar with normal pancreatic cells with the same changing trend for the expression of NF-κB, TNF-α, SIRT1, and LC3 II after picroside II treatment." (PMID 28713490, 2017). "Recent efforts have identified multiple dysregulated signaling pathways in pancreatic cancer development and progression, many of which appear to be reasonable targets including PI3K/mTOR, SIRT1, and ALK." (PMID 26369833, 2015). "miR-373 regulates MMP activity by modulating MAPK signaling or targeting mTOR and SIRT1 in human fibrosarcoma cells, and by targeting ZIP4 in pancreatic cancer." (PMID 26103880, 2015). "In the present study, resveratrol inhibited the expression of SIRT1, SIRT2 and SIRT3 in pancreatic cancer cells, thus suggesting a role of SIRT1 as a tumor suppressor in cancer cells." (PMID 21980390, 2011). "Therefore, the upregulation of SIRT1 enhances the stability of the HIF-1α protein through deacetylation, promoting Gemcitabine resistance in normoxic pancreatic cancer cells." (PMID 39928285, 2025). "Consequently, upregulated SIRT1 enhances HIF-1α stability through deacetylation, resulting in glycolysis and GEM resistance in recipient pancreatic cancer cells." (PMID 40004471, 2025). "The SIRT1 agonists SRT1720 and SRT1460 are more effective in pancreatic cancer cells." (PMID 39479446, 2024). "Additionally, one study has revealed that SIRT1 directly suppresses β-catenin, a key oncogenic molecule upregulated by PAUF in pancreatic cancer cells, thereby inhibiting tumor cell proliferation." (PMID 39682281, 2024). "Using SIRT1 activators such as SRT1720, SRT1460, and SRT3025 was reported to effectively inhibit tumor growth in a xenograft model and to promote the survival of pancreatic cancer cells." (PMID 37715252, 2023). "Compound AC-93253 and Salermide (chosen at a concentration at which SIRT-2, but not SIRT-1, is inhibited) blocked cell proliferation and downregulated the c-Myc and N-Myc oncoproteins in neuroblastoma and in pancreatic cancer." (PMID 36080416, 2022). "Furthermore, the SIRT1/CRL4B complex contributes to the epigenetic silencing of tumor suppressors, also playing an important role in pancreatic cancer tumorigenesis and regulating the properties of CSCs." (PMID 34163012, 2021). "Furthermore, we found that SIRT1 and CUL4B collectively promote the proliferation, autophagy, and invasion of pancreatic cancer cells." (PMID 34163012, 2021). "It has been reported that SIRT1 is overexpressed in pancreatic cancer tissues and is a promoter of the occurrence and metastasis of pancreatic cancer; however, SIRT1 has the opposite effect in oral squamous cell carcinoma, which inhibits EMT through the SIRT1/Smad4/MMP7 pathway." (PMID 34934771, 2021). "Furthermore, analysis of a published clinical dataset (GSE15471) revealed that compared with normal pancreatic tissues, SIRT1 and CUL4B expression increased in pancreatic tumor samples, while FOXO3 and GRHL3 significantly decreased." (PMID 34163012, 2021). "Next, we investigated whether SIRT1 and CUL4B affect stem-like phenotypes in pancreatic cancer cells." (PMID 34163012, 2021). "Besides inhibiting SIRT1 and PARP1, NAM has shown to inhibit the oncogenic KRAS/AKT pathway in skin and pancreatic cancers, modulate the expression of Myc oncogene in bladder cancer, and suppress IGF-1 in HCC." (PMID 32245130, 2020). "Combined therapy of GEM with inhibition of SIRT1, improve efficacy and survival time in a pancreatic cancer xenogeneic mice model, compared with single inhibition of SIRT1, or single GEM therapy, probably due to the implication of SIRT1 in chemo-sensitivity of pancreatic cancer cells." (PMID 33042011, 2020). "MiR-601 also inhibits SIRT1 and its expression is significantly lower in cancer samples, especially in metastatic compared to non-metastatic pancreatic cancer tissues." (PMID 33042011, 2020).